BCL2 (BCL2 apoptosis regulator)
Diseases named in the same sentence as BCL2 in open-access papers (continued):
Sharing a sentence is not in itself a finding about the gene and the disease.
toxicity (1 paper, 2025). The degree to which an agent can damage an organism. "In this study, the effects of RJ at doses of 150 mg/kg and 300 mg/kg on Bax, Bcl-2, and Caspase-3 protein expression in VCR-induced liver toxicity were investigated." (PMID 40141803, 2025).
Tremor (1 paper, 2018). An unintentional, oscillating to-and-fro muscle movement about a joint axis. "Moreover, it has been reported that cardiomyocyte apoptosis is involved in the myocardial injury of tremor rats by reducing Bcl-2 and p-ERK1/2, upregulating Bax, p-JNK, and p-p38, and activating caspase-3." (PMID 30181740, 2018).
tubular adenoma (1 paper, 2021). A usually polypoid neoplasm arising from the glandular epithelium. "Large tubular adenomas (two cm or greater) also exhibited the highest level of BAX and consequently the lowest BCL2/BAX ratio." (PMID 34762658, 2021). "In tubular adenomas, but not in HPPs, pro-apoptotic BAX was strongly correlated with anti-apoptotic BCL2 (r = 0.48, p<0.0001), The survivin LI was highly correlated in both types of lesions with the KI-67 LI and with each of the proliferation-related analytes except for p16 in tubular adenomas." (PMID 34762658, 2021).
tubulovillous adenoma (1 paper, 2021). An epithelial neoplasm morphologically characterized by the presence of a villous and a tubular architectural pattern. "Tubulovillous adenomas also showed a strikingly low expression of pro-apoptotic BCL2 and a low pro- vs anti-apoptotic ratio, BCL2/BAX, despite small differences in the CASP3 LI." (PMID 34762658, 2021).
uremia (1 paper, 2024). A clinical syndrome associated with the retention of renal waste products or uremic toxins in the blood. "A prior study showed accelerated in vitro apoptosis of lymphocytes in uremia, with a particularly pronounced effect on B cells, mediated by dysregulation of Bcl-2." (PMID 38656290, 2024).
urticaria (1 paper, 2024). A vascular reaction of the skin characterized by erythema and wheal formation due to localized increase of vascular permeability. "BCL2 is known to regulate cell apoptosis, and studies have indicated that its overexpression in lymphocytes is linked to the development and progression of skin itching-related diseases such as urticaria and specific dermatitis." (PMID 39606625, 2024).
uterine corpus endometrioid carcinoma (1 paper, 2016). "For example, an L-FFL motif constituted by E2F1, miR-15b, and IQCH-AS1, and an M-FFL motif made of E2F1, miR-15b and BCL2 formed a complex L-M-FFL motif in uterine corpus endometrioid carcinoma, but only the L-FFL motif correlated with patient survival (P=0.002)." (PMID 27322142, 2016).
uterine sarcoma (1 paper, 2025). "In uterine sarcoma cells, ONC201 increased DR5 abundance, downregulated Akt and Erk phosphorylation and induced intrinsic and extrinsic apoptotic pathways without affecting the levels of Bcl-2." (PMID 40305155, 2025).
venous thromboembolism (1 paper, 2026). Occlusion of the lumen of a vein by a thrombus that has migrated from a distal site via the blood stream. "In contrast, estrogen-containing contraceptives carry a higher baseline risk for venous thromboembolism and potential CYP3A4-mediated interactions, so they are generally less appropriate in women receiving BTK or BCL-2 inhibitors or in those with additional VTE risk factors." (PMID 41546716, 2026).
viral myocarditis (1 paper, 2022). Myocarditis that is caused by an infection with a viral agent. "In addition, no apoptosis was detected in the hearts of KO mice with acute viral myocarditis: no TUNEL positive cells were detected, and the mRNA levels of Bax, Bcl-2, and cyclinD1 were not significantly different from those in the hearts of WT mice on Day 5 post-infection (TUNEL stain and RT-PCR)." (PMID 35163412, 2022).
vitamin deficiency (1 paper, 2019). A disorder that is caused by the deficiency of a vitamin. "This is probably due to overexpression of the anti-apoptotic Bcl-2 protein genes initiated by vitamin deficiency." (PMID 30705831, 2019).
Warthin tumor (1 paper, 2009). An adenoma characterized by an oncocytic, often papillary, epithelial component, dense lymphoid stroma, and cystic spaces. "Immunohistochemical results of the present study also revealed that Warthin's tumour expressed a high level of p27Kip1 and bcl-2, with p27Kip1 immunopositivity detected in all 20 cases, while 18/20 cases were bcl-2 immunopositive." (PMID 19445705, 2009). "The aim of the present study is to investigate the immunohistochemical expression of mdm-2, p27Kip1 and bcl-2 in Warthin's tumor of parotid gland and also to clarify the role of these proteins in the behavior of that tumor." (PMID 19445705, 2009). "Twenty paraffin blocks of cases previously diagnosed as Warthin's tumor were collected for immunohistochemical staining with primary antibodies against mdm-2, p27Kip1 and bcl-2 using streptavidin-biotin immunoperoxidase staining system." (PMID 19445705, 2009). "• Elevated bcl-2 expression in Warthin's tumor suggests a possible protection against p27Kip1-mediated apoptosis." (PMID 19445705, 2009). "Bcl-2-Immunonegativity noted in only 2 out of 20 cases of the present study might indicated failure of bcl-2 to block apoptosis in certain circumstances such as apoptosis induced by cytotoxic T-lymphocytes, a finding that might indicated a reactive nature of the lymphoid tissue in Warthin's tumor." (PMID 19445705, 2009).
Wolfram syndrome 2 (1 paper, 2013). Any Wolfram syndrome in which the cause of the disease is a mutation in the CISD2 gene. "It was implicated in human pathology (Wolfram Syndrome 2) and in BCL-2 mediated antagonization of Beclin 1-dependent autophagy and depression of ER calcium stores." (PMID 23717386, 2013).
tumor (4,786 papers, 1994 to 2026). "An increased Bax/Bcl-2 ratio reduces cellular resistance to apoptosis activation, leading to increased cell death and a decreased risk of tumor formation." (PMID 40732250, 2025). "This inverse relationship is particularly relevant as lower miR-383 levels are also associated with tumor cell resistance to 5-fluorouracil (5-FU), suggesting that elevated Bcl-2 contributes to drug resistance by inhibiting chemotherapy-induced apoptosis." (PMID 40841912, 2025). "In BC and its drug-resistant variants, curcumin inhibits tumor proliferation through the reduction in Bcl-2 and COX-2 expression." (PMID 41515171, 2025). "When C6 glioma cells were implanted in Wistar rats, HSP prevented tumour growth by activating caspase-3 and -9, raising the Bax/Bcl-2 ratio, which caused apoptosis, and downregulating the HIF-1α, VEGF, and VEGFR2 signalling pathways." (PMID 40427522, 2025). "Detailed immunoblot analyses revealed that compounds 11a and 11b decreased the expression of endogenousGLI1 protein and its target genes associated with tumor progressionand proliferation, such as Cyclin D1, N-Myc, and Bcl-2, in A549 andDU-145 cancer cells." (PMID 40124057, 2025). "This promotes the transcriptional activation of anti-apoptotic genes (such as MDM2 and Bcl-2), contributing to T cell exhaustion, which is linked to diminished anti-tumor immunity." (PMID 40352941, 2025). "The expression of pro-apoptotic BAX (BCL2 associated X, apoptosis regulator) and anti-apoptotic BCL2 (BCL2 apoptosis regulator) was analysed in tumour and corresponding healthy tissue samples of patients by quantitative real-time PCR." (PMID 40821650, 2025). "The BAX/BCL2 ratio association in tumour tissuesamples with sphingolipid serum profile wasinvestigated." (PMID 40821650, 2025). "Antiapoptotic proteins like Bcl-XL and Bcl-2 are intricately associated with the initiation, advancement, and resistance to the treatment of neoplasms." (PMID 40224721, 2025). "Their analysis demonstrated a significant association between elevated BCL2 expression and tumor site." (PMID 41189865, 2025). "Although BCL2 and Cyclin D1 showed associations with tumor aggressiveness, their prognostic roles remain uncertain." (PMID 41189865, 2025). "Many neoplasms develop resistance to apoptosis through inactivating mutations in tumor suppressor genes, overexpression of anti-apoptotic proteins such as BCL-2, or alterations in cellular caspase signaling." (PMID 41369416, 2025). "This selective effect was associated with BAX and caspase-3 upregulation, BCL-2 downregulation, and apoptotic morphological changes detected exclusively in tumor cells." (PMID 41300439, 2025). "Overexpression of Bcl-2 and increased mast cell infiltration have also been associated with tumor progression and recurrence risk." (PMID 40995404, 2025). "The underlying mechanism is likely the downregulation of Bcl-2/Bax protein expression to trigger tumor cell apoptosis, coupled with the suppression of matrix metalloproteinases MMP-2 and MMP-9 expression to impede cell metastasis." (PMID 40332041, 2025). "One of the hallmarks of GB is the abnormal expression of anti-apoptotic proteins such as BCL-2, which is associated with tumor survival and the resistance of malignant cells to radiotherapy and chemotherapy." (PMID 39940838, 2025).
tumor (continued). "BCL-2 inhibitor Venetoclax enhances tumor cell susceptibility to CAR-T cells by antagonizing BCL-2-mediated anti-apoptotic signaling and inducing G1-phase cell cycle arrest." (PMID 41169368, 2025). "On this line, BCL2 expression was also often associated with features of less aggressive tumor biology." (PMID 40806359, 2025). "Our findings demonstrated that IRF4‐mediated SOX9 induction in BCL2‐overexpressing DLBCL was associated with tumour progression, suggesting the potential therapeutic implication of the IRF4‒SOX9 signalling axis in this type of DLBCL." (PMID 40356256, 2025). "AKT promotes tumor cell survival by phosphorylating pro-apoptotic proteins, such as Bcl-2-associated death promoter and Caspase-9, thereby enhancing the cells’ ability to evade apoptosis, and it also plays a crucial role in tumor invasion and metastasis." (PMID 40141978, 2025). "BCL2, a key apoptotic gene, is widely expressed in various tumor cells and is closely associated with the carcinogenesis of many malignant diseases." (PMID 39086951, 2024). "The BCL2 family of proteins plays essential roles in controlling cell survival; therefore, their altered expression and the appearance of BCL2 somatic mutations are associated with tumor progression, drug resistance, and disease recurrence." (PMID 38670940, 2024). "DSP identified the BCL-2 associated agonist of cell death (BAD) protein as the most significantly upregulated protein in the tumor center." (PMID 39217197, 2024). "By down-regulating the expression of Bcl-2, Erianin can weaken the anti-apoptotic ability of tumor cells, making them more susceptible to induction of apoptosis signals." (PMID 39605083, 2024). "They found that BCL-2 expression was associated with longer survival and reduced tumor aggressiveness, particularly in patients with lower tumor grades and positive hormone receptor status." (PMID 39685591, 2024). "Somatic mutations affecting the cytosolic domains of BCL2 correlate with poor prognosis and a loss of sensitivity to anti-tumor treatments, which has prompted the development of alternative therapeutic strategies for affected cancer patients." (PMID 38670940, 2024). "Seventy-one cases were examined to assess BCL-2 expression and its association with other prognostic indicators, such as estrogen (ER) and progesterone (PR) receptors, tumor size, and lymph node status." (PMID 39685591, 2024). "miRNA-34 regulates tumor-cell behavior by targeting Notch, c-Met, and Bcl-2 expression, which are associated with tumor-cell self-renewal and survival." (PMID 38927885, 2024). "Different tumor subtypes have different constitutional BCL-2 expression patterns, which can be caused by a number of different factors." (PMID 39906657, 2024). "Recent studies revealed that Venetoclax in addition to potently blocking BCL-2 causes cellular responses that support anti-tumor activity including metabolic reprogramming and activation of the integrated stress response." (PMID 39048751, 2024). "A previous study has indicated that Gngt2 deficiency can promote cell proliferation in tumor cells by upregulating Bcl‐2 expression." (PMID 39417697, 2024). "The occurrence of cancer is typically associated with abnormal mutations in tumor suppressor genes and oncogenes, such as the aberrant expression of the anti-apoptotic protein B-cell lymphoma 2 (BCL-2)." (PMID 38685028, 2024). "Tumor cells can acquire resistance to apoptosis by the expression of anti-apoptotic proteins such as Bcl-2 or by the downregulation or mutation of pro-apoptotic proteins such as BAX." (PMID 39126093, 2024).
tumor (continued). "Overexpression of BCL-2 is often observed in various cancers, where it is associated with tumor resistance to apoptosis and an increased capacity for cell survival under stress conditions." (PMID 39685591, 2024). "The AgNPs also enhance the expression of CASP3, CASP9, and miR-192 proteins and decrease the expression of Bcl-2 genes in tumour cells, that in turn causes apoptosis." (PMID 37668757, 2024). "While high Bcl-2 expression can render some tumor cells more susceptible to apoptosis induction, it can also contribute to therapy resistance by inhibiting the apoptotic pathways of specific chemotherapeutic agents or targeted therapies." (PMID 39840282, 2024). "According to Chun-Yan Sun, hsa-miR-15a acts as a putative tumor suppressor by targeting the oncogene B-cell lymphoma (BCL-2), which has been implicated in apoptosis and proliferation." (PMID 39062015, 2024). "The overexpression of certain anti-apoptotic oncogenes (i.e., the Bcl-2 gene) and impaired apoptosis in various types of tumors have been associated with resistance and can contribute to tumor cell division." (PMID 38612619, 2024). "The effectiveness of BP1003 is likely due to its ability to decrease STAT3 levels, which leads to decreased expression of its downstream targets, such as vimentin and Bcl-2, which have both been associated with tumor aggression and poor prognosis." (PMID 39200368, 2024). "According to the examination of patient samples, breast and colorectal cancer liver metastasis was linked to Bcl-2 expression in tumor cells." (PMID 38223131, 2024). "Esculetin has been shown to cause apoptosis and decrease proliferation and tumor development in both in vitro and in vivo experiments by causing a cell cycle arrest in the S phase, where Bax, caspase‐3, and ‐9 are elevated, and Bcl‐2 is downregulated." (PMID 38062981, 2024). "Bcl-2 proteins block apoptosis in tumor cells, whereas Bcl-2-associated X protein (Bax) promotes apoptosis." (PMID 39086397, 2024). "The results showed that supernatant of M1-iBMDMs promoted the expression of apoptosis associated genes, including APAF1 and Caspase-9 in tumor cells, and decreased the level of protective molecule BCL2." (PMID 38650937, 2024). "The presented system not only directly delivered camptothecin to cancer cells, but also decreased the expression of the anti-apoptotic protein Bcl-2, which is associated with the inhibition of tumor growth in vivo." (PMID 39272802, 2024). "The overexpression of the BCL2 is linked to tumor initiation, progression, and resistance to current anticancer therapies." (PMID 39011503, 2024). "The interaction of miRNA and Bcl-2 was further studied in 2015, where hypoxia was associated with low levels of miR-15a, promoting invasion and migration of tumor cells." (PMID 37720343, 2023). "Their studies demonstrated significant inhibition of tumor progression associated with Bcl-2 overexpression, both in vitro and in vivo." (PMID 37609372, 2023).